NUTM2E (NUT family member 2E)
Synonyms: FAM22E
Tractability: No criterion of Open Targets' tractability assessment is met for any kind of drug.
Gene: Protein-coding gene on chromosome 10 (79,826,739 to 79,850,878, forward strand). Ensembl gene ENSG00000228570.
Subcellular location (Human Protein Atlas): Nuclear bodies
Homologues: Orthologues: macaque NUTM2A (76% identical), rat Nutm2 (34% identical), mouse Nutm2 (33% identical). Paralogues in human: NUTM2B (99% identical), NUTM2A (98% identical), NUTM2D (89% identical), NUTM2F (72% identical), NUTM2G (71% identical), NUTM1 (41% identical).
Diseases named in the same sentence as NUTM2E in open-access papers:
NUTM2E is named in the same sentence as 2 diseases in open-access papers, as found by Europe PMC text mining. Sharing a sentence is not in itself a finding about the gene and the disease.
NUTM2E shares sentences with these, for which no sentence is quoted: cardiomyopathy (1 paper); heart failure (1).